HEATR9 (HEAT repeat containing 9)
Synonyms: C17orf66; FLJ32830
Tractability: No criterion of Open Targets' tractability assessment is met for any kind of drug.
Gene: Protein-coding gene on chromosome 17 (35,854,946 to 35,868,891, reverse strand). Ensembl gene ENSG00000270379.
Gene Ontology:
Molecular function: protein binding
Genetic constraint (gnomAD): Loss-of-function variants: 55 observed, 71.79 expected, observed/expected ratio (o/e) 0.77, 90% interval 0.62 to 0.96. The upper end of that interval is the gene's LOEUF score, 0.96, which puts it in group 4 of 6, group 1 being the genes least tolerant of losing a copy. Missense variants: 662 observed, 706.7 expected, observed/expected ratio (o/e) 0.94, 90% interval 0.88 to 1. Synonymous variants: 241 observed, 266.32 expected, observed/expected ratio (o/e) 0.9, 90% interval 0.81 to 1.01.
Homologues: Orthologues: chimpanzee HEATR9 (98% identical), macaque HEATR9 (97% identical), dog HEATR9 (77% identical), pig HEATR9 (73% identical), rabbit HEATR9 (72% identical), guinea pig HEATR9 (72% identical), rat Heatr9 (61% identical), mouse Heatr9 (60% identical).
Diseases named in the same sentence as HEATR9 in open-access papers:
HEATR9 is named in the same sentence as 10 diseases in open-access papers, as found by Europe PMC text mining. Sharing a sentence is not in itself a finding about the gene and the disease. The quoted sentences say what the papers report.
viral infection (2 papers, 2020 to 2022). "We then wanted to confirm the induction of Heatr9 during influenza virus infection by qRT-PCR from infected mouse lungs and to determine the kinetic of expression during acute virus infection." (PMID 32678841, 2020). "Our studies identify Heatr9 as a novel inflammatory and virus infection induced gene that can regulate the induction of specific cytokines." (PMID 32678841, 2020). "Having confirmed the induction of Heatr9 expression in vivo during influenza virus infection in the lungs of mice, we wanted to confirm Heatr9 upregulation following virus infection in vitro." (PMID 32678841, 2020). "In this model, we were able to show that direct viral infection of A549 cells with either influenza virus or RSV-A2 was capable of inducing Heatr9 expression." (PMID 32678841, 2020). "We confirm Heatr9’s expression in vitro and in vivo during virus infection and correlate it with viral burden." (PMID 32678841, 2020). "This suggests a graded expression of Heatr9 depending upon viral burden, indicating that greater viral transcripts stimulate greater Heatr9 induction and further support the idea that viral infection drives Heatr9 expression." (PMID 32678841, 2020). "Hence, HEATR9 is said to be involved in inflammatory and virus infections serving as a regulator of specific cytokines." (PMID 35173218, 2022). "This suggested that Heatr9 induction is part of a response to viral infection." (PMID 32678841, 2020). "Heatr9 knockdown during viral infection was shown to affect chemokine expression." (PMID 32678841, 2020). "Use of A549 cells showed that transfer of infected culture supernatant or cytokines used in combination were capable of inducing Heatr9 expression, albeit not to the same extent as direct viral infection." (PMID 32678841, 2020). "Transfer of infected culture supernatant from PR8-GFP infected A549 culture supernatants at 24 hours post infection was capable of inducing Heatr9 expression, albeit not as strongly as direct virus infection." (PMID 32678841, 2020). "We were not the first to identify Heatr9 as previous studies have identified it in mouse models of Staphylococcus aureus infections, as well as in RNA sequencing data from various virus infections, both in vitro in human cell lines and in vivo in mouse infections." (PMID 32678841, 2020). "As chemokines are also expressed in many tissues in uninfected status, Heatr9 could play a role in low level homeostatic chemokine induction in the absence of viral infection." (PMID 32678841, 2020). "As the bystander cells in the RNA-Seq data suggested, Heatr9 could be upregulated in the absence of direct viral infection." (PMID 32678841, 2020).
autoimmune disease (1 paper, 2020). A disorder resulting from loss of function or tissue destruction of an organ or multiple organs, arising from humoral or cellular immune responses of the individual to their own tissue constituents. "Its cytokine induction and its regulation of chemokine expression also raise the question whether Heatr9 is regulated in inflammatory and autoimmune diseases." (PMID 32678841, 2020).
influenza (1 paper, 2019). An acute viral infection of the respiratory tract, occurring in isolated cases, in epidemics, or in pandemics; it is caused by serologically different strains of viruses (influenzaviruses) designated A, B, and C, has a 3-day incubation period, and usually lasts for 3 to 10 days. "Genes such as HEATR9, IL4I1, TNFSF13B (BAFF), and PDCD1 (PD-1) are recently implicated in influenza pathogenesis and mucosal defense, thereby signifying the role of the nasal epithelium against influenza infection." (PMID 31461941, 2019).
lung adenocarcinoma (1 paper, 2020). A carcinoma that arises from the lung and is characterized by the presence of malignant glandular epithelial cells. "Using a relevant human lung adenocarcinoma cell line, A549 cells, we quantified the induction of Heatr9 at 24 hours post infection with 1 MOI A/Puerto Rico/8/1934-GFP." (PMID 32678841, 2020).
male infertility (1 paper, 2022). The inability of the male to effect fertilization of an ovum after a specified period of unprotected intercourse. "There are no available studies on its impact on male infertility; however, studies investigating the impact or effect of testicular infection or inflammation such as orchitis may explore the role of HEATR9 and how this can help with future therapeutics." (PMID 35173218, 2022).
infection (2 papers, 2020 to 2022). The state of being infected such as from the introduction of a foreign agent such as serum, vaccine, antigenic substance or organism. "HEAT repeat containing 9 (HEATR9) is an infection-responsive gene that affects cytokine production in alveolar epithelial cells." (PMID 35173218, 2022). "Infection of A549 cells with 1 MOI of RSV-A2 induced Heatr9 expression with a significant positive correlation when plotted against interferon stimulated gene 15 (Isg15) induction." (PMID 32678841, 2020). "Here we report that during infection with influenza virus, Heatr9 transcripts are upregulated in the lung, specifically within alveolar epithelial cells." (PMID 32678841, 2020). "To study the function of Heatr9 during influenza virus infection, we knocked down Heatr9 expression via transfection of gene-targeting gapmers into A549 cells followed by infection." (PMID 32678841, 2020). "It was reported that the knockdown of HEATR9 during infection affected chemokine expression." (PMID 35173218, 2022). "As Heatr9 appeared to be induced in the absence of direct infection, we attempted to identify if any cytokines were capable of inducing Heatr9 expression in the absence of infectious virus." (PMID 32678841, 2020). "The presence of this domain does not give a strong indication as to what the function of Heatr9 is during infection as HEAT repeats can be found in a number of different proteins." (PMID 32678841, 2020).
HEATR9 also shares sentences with these, for which no sentence is quoted: malaria (1 paper); orchitis (1); parasite infections (1); pulmonary disease (1).